TLCD3A (TLC domain containing 3A)
Synonyms: FAM57A; FLJ22282; CT120
Tractability: Antibody: its Gene Ontology location is reachable by antibodies, with high confidence; UniProt places it where antibodies can reach, with medium confidence; UniProt predicts a signal peptide or a membrane-spanning region.
Gene: Protein-coding gene on chromosome 17 (732,412 to 742,968, forward strand). Ensembl gene ENSG00000167695.
Subcellular location: Cell membrane
Gene Ontology:
Molecular function: protein binding
Biological process: lipid homeostasis
Cellular component: plasma membrane; endoplasmic reticulum; membrane
Genetic constraint (gnomAD): Loss-of-function variants: 17 observed, 27.22 expected, observed/expected ratio (o/e) 0.62, 90% interval 0.43 to 0.94. The upper end of that interval is the gene's LOEUF score, 0.94, which puts it in group 3 of 6, group 1 being the genes least tolerant of losing a copy. Missense variants: 332 observed, 317.68 expected, observed/expected ratio (o/e) 1.05, 90% interval 0.95 to 1.14. Synonymous variants: 143 observed, 132.99 expected, observed/expected ratio (o/e) 1.08, 90% interval 0.94 to 1.24.
Homologues: Orthologues: chimpanzee TLCD3A (99% identical), macaque TLCD3A (96% identical), dog TLCD3A (88% identical), pig TLCD3A (83% identical), guinea pig TLCD3A (79% identical), rat Tlcd3a (77% identical), rabbit TLCD3A (77% identical), mouse Tlcd3a (73% identical), tropical clawed frog tlcd3a (55% identical), zebrafish tlcd3a (46% identical), Drosophila melanogaster CG17841 (31% identical). Paralogues in human: TLCD3B (47% identical), TLCD4 (20% identical), CLN8 (18% identical), TLCD1 (15% identical), TLCD2 (15% identical).
Diseases named in the same sentence as TLCD3A in open-access papers:
TLCD3A is named in the same sentence as 15 diseases in open-access papers, as found by Europe PMC text mining. Sharing a sentence is not in itself a finding about the gene and the disease.
TLCD3A shares sentences with these, for which no sentence is quoted: cancer (5 papers); prostate carcinoma (4); tumor (4); head and neck cancer (2); lung carcinoma (2); breast carcinoma (1); cervical cancer (1); colon cancer (1); hepatocellular carcinoma (1); infection (1); influenza (1); liver cancer (1); pancreatic cancer (1); prostate tumors (1); sclerosteosis 1 (1).